RHCG (Rh family C glycoprotein)
Description:
Ammonium transporter involved in the maintenance of acid-base homeostasis. Transports ammonium and its related derivative methylammonium across the plasma membrane of epithelial cells likely contributing to renal transepithelial ammonia transport and ammonia metabolism. Postulated to primarily mediate an electroneutral bidirectional transport of NH3 ammonia species according to a mechanism that implies interaction of an NH4(+) ion with acidic residues of the pore entry followed by dissociation of NH4(+) into NH3 and H(+). As a result NH3 transits through the central pore and is protonated on the extracellular side reforming NH4(+). May act as a CO2 channel providing for renal acid secretion.
Synonyms: C15orf6; PDRC2; RHGK; SLC42A3
Tractability: Antibody: UniProt places it where antibodies can reach, with high confidence; its Gene Ontology location is reachable by antibodies, with high confidence; UniProt predicts a signal peptide or a membrane-spanning region.
Gene: Protein-coding gene on chromosome 15 (89,471,398 to 89,496,614, reverse strand). Ensembl gene ENSG00000140519.
Subcellular location: Cell membrane; Apical cell membrane
Pathways (Reactome):
Transport of small molecules: Rhesus glycoproteins mediate ammonium transport
Gene Ontology:
Molecular function: ammonium channel activity; ankyrin binding; carbon dioxide transmembrane transporter activity; identical protein binding; protein binding
Biological process: ammonium transmembrane transport; intracellular monoatomic ion homeostasis; transepithelial ammonium transport; amine transport; ammonium homeostasis; epithelial cell differentiation; homeostatic process; ammonium excretion; carbon dioxide transmembrane transport
Cellular component: apical plasma membrane; basolateral plasma membrane; extracellular exosome; plasma membrane; cytoplasmic vesicle; membrane
Genetic constraint (gnomAD): Loss-of-function variants: 39 observed, 55.57 expected, observed/expected ratio (o/e) 0.7, 90% interval 0.54 to 0.92. The upper end of that interval is the gene's LOEUF score, 0.92, which puts it in group 3 of 6, group 1 being the genes least tolerant of losing a copy. Missense variants: 635 observed, 651.26 expected, observed/expected ratio (o/e) 0.98, 90% interval 0.91 to 1.04. Synonymous variants: 250 observed, 253.4 expected, observed/expected ratio (o/e) 0.99, 90% interval 0.89 to 1.1.
Homologues: Orthologues: chimpanzee RHCG (99% identical), macaque RHCG (97% identical), pig RHCG (79% identical), rat Rhcg (79% identical), mouse Rhcg (78% identical), dog RHCG (78% identical), rabbit RHCG (71% identical), tropical clawed frog rhcg (65% identical), zebrafish rhcga (65% identical), zebrafish rhcgb (63% identical), zebrafish rhcgl1 (62% identical), guinea pig RHCG (60% identical), and 3 more. Paralogues in human: RHBG (52% identical), RHAG (46% identical), RHD (28% identical), RHCE (28% identical).
Diseases named in the same sentence as RHCG in open-access papers:
RHCG is named in the same sentence as 32 diseases in open-access papers, as found by Europe PMC text mining. Sharing a sentence is not in itself a finding about the gene and the disease. The quoted sentences say what the papers report.
prostate carcinoma (3 papers, 2017 to 2019). A carcinoma that arises from epithelial cells of the prostate gland. "Here, using two large prostate cancer patient cohorts, we identified and independently validated RHCG, TCAF1, and the 2-gene panel RHCG-TCAF1 as novel independent adverse predictors of BCR after RP." (PMID 28052017, 2017). "We found that hypermethylation of COL4A6, CYBA, LINC01341, and RHCG was highly prostate cancer-specific, suggesting particularly promising diagnostic potential for these genes." (PMID 28052017, 2017). "Notably, they included DMRs close to many genes previously implicated in prostate cancer (e.g., NEAT1, MTOR, RHCG, KCNC2, WT1, HOXC12, KMT2B)." (PMID 30318509, 2018). "This is the first study to show a prognostic biomarker potential for RHCG and TCAF1 methylation in prostate cancer." (PMID 28052017, 2017). "This is the first study to demonstrate a significant prognostic value of RHCG and TCAF1 hypermethylation in prostate cancer." (PMID 28052017, 2017). "Moreover, an important future task will be to investigate whether methylation of RHCG and TCAF1 can also predict prostate cancer aggressiveness at the time of diagnosis based on analysis of DNBs or even liquid biopsies, in order to guide treatment decisions." (PMID 28052017, 2017).
psoriasis (3 papers, 2014 to 2026). An autoimmune condition characterized by red, well-delineated plaques with silvery scales that are usually on the extensor surfaces and scalp. "Furthermore, we integrated single-cell RNA sequencing (scRNA-seq) and spatial transcriptomics sequencing (ST-seq) technologies to investigate how CBDF modulates RHCG-associated signaling pathways in the treatment of psoriasis." (PMID 40678620, 2025). "Our previous studies identified RHCG as a marker of abnormal KC differentiation and DC activation in psoriasis." (PMID 40678620, 2025). "Our research group has previously explored the role of RHCG in the pathogenesis of psoriasis, demonstrating its critical involvement in keratinocyte dysregulation and inflammatory responses." (PMID 40678620, 2025). "Our previous investigations have revealed that Rh family C glycoprotein (RHCG) may serve as a critical factor in the pathogenesis of psoriasis, particularly by influencing the abnormal differentiation of keratinocytes and the activation of DCs." (PMID 40678620, 2025). "Namely, RHCG, TCN1, KLK6, and LCN2 were chosen for psoriasis and CCL17, NCF4, BATF3, and CLEC4G as ACD-specific genes." (PMID 25058585, 2014).
esophageal cancer (2 papers, 2019 to 2024). A primary or metastatic malignant neoplasm involving the esophagus. "Research has shown that RHCG plays an important role in various cancers, such as cervical squamous cell carcinoma and esophageal cancer, but has a procarcinogenic effect on gastric cancer." (PMID 38430394, 2024).
abortion (1 paper, 2014). the ending of pregnancy by removing a fetus or embryo before it can survive outside the uterus. "The abortion (2.4% vs. 2.0%; p=0.929) and ectopic pregnancy rates (1.2% vs. 1.0%; p=0.976) were comparable between groups of rhCG and placebo respectively." (PMID 24799855, 2014).
astrocytoma (1 paper, 2018). "However, they did not detect RhBG and RhCG mRNA in 1321N1 astrocytoma cells." (PMID 30134917, 2018).
cervical cancer (1 paper, 2019). A primary or metastatic malignant neoplasm involving the cervix. "Recently, a minority of studies have reported that RHCG was frequently downregulated in esophageal and tongue squamous cell carcinomas and cervical cancer, while strongly expressed in multiple squamous epithelia." (PMID 31170090, 2019). "Recent studies revealed that RHCG could exert suppression effects on cell proliferation, migration, and invasion in esophageal squamous cell carcinoma and cervical cancer." (PMID 31170090, 2019).
chronic kidney disease (1 paper, 2026). Impairment of the renal function secondary to chronic kidney damage persisting for three or more months. "A machine learning-selected biomarker panel (PDK4, RHCG, FBP1) demonstrated strong diagnostic value (area under the curve, AUC > 0.9), with consistent downregulation across multiple chronic kidney diseases." (PMID 41481634, 2026).
esophageal squamous cell carcinoma (1 paper, 2019). Esophageal squamous cell carcinoma (ESCC) is a type of esophageal carcinoma (EC) that can affect any part of the esophagus, but is usually located in the upper or middle third. "Previous evidence has shown that RHCG is downregulated in esophageal squamous cell carcinoma and tongue squamous cell carcinoma, but expressed in multiple normal squamous epithelia." (PMID 31170090, 2019).
laryngeal squamous cell carcinoma (1 paper, 2022). A squamous cell carcinoma that arises from the larynx. "A similar tumorigenic function of miR-1248 was reported in laryngeal squamous cell carcinoma (LSCC) where low expression of circular RNA hsa_circ_0036722 could not sponge miR-1248, thus promoting proliferation by inhibiting the tumour suppressor gene RHCG." (PMID 35715818, 2022).
lung carcinoma (1 paper, 2024). "Experimental validation of signature genes in the CS2 subtype showed that inhibiting the expression of RHCG and TRPA1 could enhance the sensitivity of lung cancer cells to radiation." (PMID 38430394, 2024). "Our findings suggest that the inhibition of RHCG and TRPA1 enhances the sensitivity of lung cancer cells to radiation and may provide a new target for the combination of radiotherapy and immunotherapy for lung cancer treatment." (PMID 38430394, 2024).
nephropathies (1 paper, 2026). "Further analysis revealed that while RHCG exhibited distinct expression patterns in DKD compared to other nephropathies, FBP1 and PDK4 showed comparable expression levels across disease types." (PMID 41481634, 2026).
oncocytoma (1 paper, 2017). "The chRCC and oncocytoma samples displayed almost identical gene expression profiles for MAL, TMEM255A, RHCG, ATP6V0A4, STAP1, and DEFB1, as demonstrated by both RNA microarray and RNA sequencing, which is in agreement with the known fact that chRCC and oncocytoma are related neoplasms." (PMID 29208006, 2017).
prostate tumors (1 paper, 2017). "More specifically, we observed promoter hypermethylation and downregulation of RHCG in prostate tumors, which is consistent with previous reports of RHCG downregulation in kidney and oesophagal carcinomas." (PMID 28052017, 2017).
renal carcinoma (1 paper, 2023). A carcinoma arising from the epithelium of the renal parenchyma or the renal pelvis. "Although the role of RHCG in PC is unknown, it has been identified as a tumor-type marker in renal cancer." (PMID 37124494, 2023).
tumor (10 papers, 2017 to 2025). "Recently, promoter hypermethylation of CHL1 and RHCG, two novel tumor suppressor candidates, has been reported to be associated with poor differentiation and increased invasion of ESCC, as well as advanced tumor stage and decreased overall survival." (PMID 33194605, 2020). "According to intercellular communication analysis, we report a regulatory network that could facilitate the keratinization of RHCG+ epithelial cells, eventually causing tumour progression." (PMID 38906852, 2024). "In addition, the molecular mechanisms underlying the tumor suppressive functions of RHCG have been previously investigated." (PMID 31170090, 2019). "The study identified a regulatory network facilitating RHCG+ epithelial cell keratinization, contributing to tumor progression." (PMID 40575267, 2025). "In summary, our study identified RHCG as a candidate biomarker correlated with HNSCC tumor progression and dismal prognosis, which acted as a tumor suppressor gene by playing a pivotal role in impeding tumorigenicity and metastasis in HNSCC." (PMID 31170090, 2019). "It was shown that proportion of HNSCC patients with RHCG low expression was significantly increased in HNSCC patients with a more advanced tumor stage and lymph node metastasis." (PMID 31170090, 2019). "Conversely, the tumor volume of RHCG overexpression group was much smaller than NC group." (PMID 31170090, 2019). "In the present study, RHCG was identified to be significantly downregulated in HNSCC tissues and correlated with tumor progression based on TCGA dataset." (PMID 31170090, 2019). "RHCG affects the proliferation, motility, and metastasis of tumor cells However, no study has explored the expression and potential functions of RHCG in LUAD." (PMID 38430394, 2024). "Strikingly, low expression of RHCG was correlated with previously established HNSCC-specific progressive signatures such as “CROMER metastasis up”, “RICKMAN metastasis up” and “RICKMAN tumor differentiated well vs poorly up”." (PMID 31170090, 2019). "RHCG silencing in HNSCC cell lines CAL27 and FADU could effectively promote cell viability, colony formation and cell migration and tumor formation in nude mice, while ectopic expression of RHCG in JHU011 cells could suppress these functions, which was in consistence with previous studies." (PMID 31170090, 2019). "Experimental design: Eight novel candidate markers, COL4A6, CYBA, TCAF1 (FAM115A), HLF, LINC01341 (LOC149134), LRRC4, PROM1, and RHCG, were selected from Illumina Infinium HumanMethylation450 BeadChip analysis of 21 tumor (T) and 21 non-malignant (NM) prostate specimens." (PMID 28052017, 2017).
cancer (4 papers, 2017 to 2024). A tumor composed of atypical neoplastic, often pleomorphic cells that invade other tissues. "The protein encoded by RHCG is primarily associated with cell ion homeostasis and protein binding, and has been found to be linked to several types of cancers." (PMID 37783723, 2023). "Since DNA promoter hypermethylation is commonly implicated in inactivation of tumor suppressor genes in cancers, we then investigated whether the RHCG promoter hypermethylation may impair RHCG expression in HNSCC." (PMID 31170090, 2019). "Hub gene identification combined with survival analyses determined RHCG as a candidate biomarker for cancer progression and prognosis prediction." (PMID 31170090, 2019). "A pan-cancer study of RHCG expression pattern based on database revealed that RHCG was downregulated in multiple cancers, with HNSCC listed as the most significantly downregulated." (PMID 31170090, 2019). "From this list, 8 novel top candidate genes were selected based on their display of highly cancer-specific hypermethylation over multiple adjacent promoter-associated DMCs: COL4A6, CYBA, HLF, LINC0134 (LOC149234), LRRC4, PROM1, RHCG, and TCAF1 (FAM115A)." (PMID 28052017, 2017).
RHCG also shares sentences with these, for which no sentence is quoted: gastric cancer (2 papers); infertile (2); acute liver failure (1); breast carcinoma (1); cervical squamous cell carcinoma (1); cryptorchidism (1); cutaneous melanoma (1); glioblastoma multiforme (1); glioma (1); head and neck squamous cell carcinoma (1); liver disease (1); lung squamous cell carcinoma (1); metabolic disorders (1); neuroblastoma (1); psoriatic arthritis (1); tongue squamous cell carcinoma (1).